INS (insulin)
Diseases named in the same sentence as INS in open-access papers (continued):
Sharing a sentence is not in itself a finding about the gene and the disease.
diabetes (continued). "Both the hyperglycaemia as well as the chronic exposure to elevated insulin levels can in their turn further diminish insulin-mediated glucose uptake, potentiating insulin resistance and eventual development of type 2 diabetes mellitus." (PMID 39114126, 2024). "Diabetes mellitus (DM) is a common endocrine system disorder characterized by inadequate insulin secretion or persistently high blood glucose levels." (PMID 38974989, 2024). "Regarding his family history, a maternal uncle had insulin-treated diabetes, recurrent strokes starting at the age of 25, and hearing loss since childhood." (PMID 39408828, 2024). "PA can increase insulin sensitivity and reduce obesity, improving glucose uptake and controlling blood sugar for diabetes prevention and treatment." (PMID 39397263, 2024). "We still needed to evaluate the proteins-based regulation of all these to evaluate the viscosol effects on the insulin signaling pathway and its role in the regulation of dyslipidemia complication in type 2 diabetes mellitus." (PMID 39759127, 2024). "When it comes to managing their diabetes and insulin needs, a patient’s intellectual capacity is a key factor." (PMID 39065641, 2024). "Patients with a history of diabetes require tailored insulin adjustments, generally a 20% increase in basal insulin with glucocorticoid initiation." (PMID 38715788, 2024). "Diabetes manifestation can be described as a “two-hit” disease, where early insulin inevitably involves disturbed insulin secretion, leading subsequently to hyperglycemia and the onset of type 2 diabetes." (PMID 38550917, 2024). "The increase of insulin production is one of the hallmarks for the diabetes treatment, as shown in29, where a library of 4640 drugs was screened at a concentration of 10 μM to search for modulators of insulin expression." (PMID 39739113, 2024). "Correspondingly, another study revealed that the decrease in glucagon and insulin levels among patients with diabetes was 10% and 15%, respectively, compared to levels in the control group." (PMID 38818523, 2024). "Patients in the lowest quartile had the longest diabetes duration, the worst glycemic control and the highest prevalence of insulin treatment, obesity, atherogenic dyslipidemia, and smoking habits." (PMID 38714557, 2024). "The main mechanisms by which diabetes intervenes are represented by the pro-inflammatory effect, insulin resistance, and excessive compensatory insulin production." (PMID 39064555, 2024). "The study also noted that the prevalence of DR in this cohort was higher than global averages, potentially reflecting more advanced disease due to prolonged diabetes duration and greater use of insulin." (PMID 39872596, 2024). "Low levels of these enzymes in diabetes patients correlate with elevated blood glucose levels due to impaired insulin action, stemming from insulin resistance or inadequate insulin secretion." (PMID 39052545, 2024). "Insulin pumps had a revolutionary impact on diabetes care through constantly administering insulin using a variety of delivery modes." (PMID 39065641, 2024). "Insulin affects the brain, heart, kidneys, bones, skin, and hair follicles and regulates blood sugar and diabetes." (PMID 39329976, 2024). "Many authors have used the NTR/MTZ system to study diabetes and diabetic pathologies through the ablation of pancreatic β‐cells when using the insulin promoter in the well‐known Tg(ins:nfsB‐mcherry) zebrafish line (abbreviated as InsNTR)." (PMID 38279951, 2024). "Our ranking concluded that age, body mass index, and insulin intake are key predictors of duration of diabetes on both populations." (PMID 38435625, 2024). "This study highlighted diabetes duration, insulin usage, age, and circulating tyrosine as important factors in detecting DKD and DR." (PMID 38546730, 2024).
diabetes (continued). "Treatment approaches mainly involve using antidiabetic drugs and insulin to maintain blood glucose levels as close to regular as possible and to delay or prevent the development of diabetes-related complications." (PMID 39534794, 2024). "Induced higher insulin sensitivity and glucose tolerance.Reduced hepatic glycogen synthesis, which may be due to inhibition of gluconeogenesis.Changes in levels of centrally circulating proteins (including proteins that may be associated with diabetes and liver disease)." (PMID 38251002, 2024). "Diabetes mellitus (DM) is a metabolic disorder characterized by chronic hyperglycemia resulting from defects in insulin secretion, insulin action, or a combination of both." (PMID 39194579, 2024). "The role of Sirtuin 1 in diabetes is well-established; it acts as a protective factor for pancreatic β-cells and promotes glucose-dependent insulin release." (PMID 39944232, 2024). "In this experiment, the effectiveness of ART and INS intervention groups was compared in rats with experimental-induced diabetes models." (PMID 38821986, 2024). "People with type 1 diabetes mellitus (T1DM) need to take multiple doses of insulin injections daily throughout their lives." (PMID 38304656, 2024). "The mean diabetes durationand percentage of insulin users were 11.99 years (SD: 8.74) and 77.21%,respectively, in the telemedicine group." (PMID 38656030, 2024). "In patients with diabetes, a larger arterial-interstitial insulin gradient and transcapillary transport time are required for insulin to reach and stimulate glucose uptake." (PMID 38788527, 2024). "Type 2 diabetes mellitus (T2D) is defined by chronic hyperglycemia due to insufficient insulin secretion or activity and decreased insulin sensitivity, known as insulin resistance (IR)." (PMID 39627194, 2024). "Although acute hyperglycemia during times of stress can benefit the body because it diverts glucose to insulin-independent tissues, chronic stress can lead to insulin resistance and diabetes." (PMID 39057600, 2024). "Higher-scoring patients derived greater benefits to their diabetes and were more likely to discontinue insulin or oral medications, especially those with a BAPT score of 50 or greater." (PMID 39174748, 2024). "In daily management of diabetes, there is an extensive focus on insulin and obstacles related to insulin." (PMID 38892551, 2024). "In such context, the severe diabetes phenotype is a consequence of the aberrant pancreatic islet maturation and function, including insulin production." (PMID 39201476, 2024). "It was previously believed that insulin hormone was primarily secreted by pancreatic β cells and that its main role was limited to glucose regulation in diabetes." (PMID 39329976, 2024). "Insulin treatment in animal models of diabetes prevents learning deficits when given at the onset of diabetes." (PMID 39139399, 2024). "Diabetes mellitus (DM) is a heterogeneous group of metabolic conditions characterized by hyperglycaemia due to impaired insulin secretion, action, or both." (PMID 39512586, 2024). "Diabetes mellitus (DM) is a serious, chronic condition that occurs when the body is unable to produce insufficient amounts of insulin or cannot effectively use the insulin it produces." (PMID 38410501, 2024). "During these times, it is essential that patients living with diabetes work with their provider to establish an action plan regarding making changes in oral medication or insulin." (PMID 39519604, 2024). "Clinical trials have highlighted that resveratrol supplementation can effectively improve blood glucose control and insulin sensitivity, making it a potential adjunct in diabetes management." (PMID 39125368, 2024). "A 74-year-old patient with type 2 diabetes mellitus received basal-bolus insulin, insulin secretagogues, and sodium glucose transporter 2 (SGLT2) inhibitors." (PMID 38414717, 2024).
diabetes (continued). "Gene therapy holds great promise for diabetes management, offering innovative approaches to deliver and manipulate the insulin gene in various tissues." (PMID 38720379, 2024). "SCFAs regulate the glycolysis and gluconeogenesis pathways and obstruct insulin signaling in peripheral tissues through the activation of GPCRs, resulting in hyperglycemia during pregnancy and diabetes." (PMID 38248846, 2024). "For older patients with diabetes, especially T1DM, if multi‐dose subcutaneous insulin injection therapy is associated with great glycemic variability and high hypoglycemia risk, insulin pump will be suggested." (PMID 38571669, 2024). "Panelists emphasized the role of diabetes structured self-management education to involve patients in insulin titration and improve treatment adherence." (PMID 38767675, 2024). "They provide education and sick-day rules to the patient, ensure adequate insulin and devices on discharge, and facilitate transfer/hand-over to the community diabetes team and outpatient clinics." (PMID 38523875, 2024). "Insulin signaling in rat lacrimal glands becomes impaired in the fourth week of diabetes, with the lacrimal gland serving as an extra pancreatic source of insulin for at least 4–7 weeks." (PMID 38534414, 2024). "With respect to Indonesia’s JKN, this public insurance has provided insulin for-free for people with diabetes using insulin." (PMID 39361609, 2024). "Recent researches have uncovered a significant link between demographic factors, including age, gender, BMI, family history of diabetes, insulin dosage, frequency of self-monitoring, type of insulin therapy, and adherence to treatment, with glycemic control." (PMID 38553464, 2024). "In this study, our data demonstrated that the diabetics had decreased body weight, blood glucose level, and serum insulin level; insulin treatment had improved the levels of blood glucose, serum insulin level, and body weight." (PMID 38961333, 2024). "This study confirms the cost-effectiveness of structured education programs for diabetes and highlights their importance for patients with type 2 diabetes who have HbA1c levels exceeding 7% and are receiving non-insulin therapy." (PMID 39639901, 2024). "AI-powered mobile apps and wearables can also provide real-time glucose monitoring, personalized feedbacks, and insulin dosage recommendations to diabetes patients." (PMID 39238969, 2024). "In cases where diabetes remains inadequately managed, there is a progressive decline in β-cell function due to either the failure of insulin secretion or the dysregulation of neuroendocrine signaling pathways." (PMID 39055304, 2024). "This study supports the proposition that individuals with pre-diabetes can benefit from Mg2+ supplements to improve insulin metabolism and potentially lower the progression from pre-diabetes to diabetes to supplement lifestyle intervention programs." (PMID 39202546, 2024). "Recognition of this high prevalence in children with diabetes is important because of the unique natural history, pathogenesis, and potential for insulin-independence in patients with A−β+ KPD." (PMID 38765897, 2024). "In 1923, August Krogh, from the University of Copenhagen, talked with Banting and Best since his wife had diabetes, and he wanted to learn more about insulin." (PMID 39691108, 2024). "The virus can infect pancreatic beta cells, which are responsible for insulin production, potentially leading to acute hyperglycemia (high blood sugar levels) and contributing to the development of diabetes." (PMID 39338165, 2024). "Diabetes is a metabolic condition that results in hyperglycemia because of flaws in insulin secretion, function, or both." (PMID 38433295, 2024). "In fly research, a high‐fat diet increases the sugar content in fly bodies, leading to the induction of fly insulin resistance and metabolic disorders such as diabetes." (PMID 39207121, 2024).
diabetes (continued). "Hypercalciuria is a clinical presentation of early diabetes and can be reduced with insulin therapy." (PMID 39685901, 2024). "In fact, there is a positive relationship between serum insulin and elevated SU levels, in healthy volunteers and people with diabetes." (PMID 39618812, 2024). "We report the case of a patient with type 2 diabetes mellitus and a history of gastric bypass surgery who presented with hypoglycemic episodes despite the disruption of all oral antidiabetic drugs and insulin analog therapy." (PMID 39071705, 2024). "A retrospective study enrolled 373 patients with diabetes reported several factors contributing to the development of DR, including older age, male gender, a longer duration of diabetes, receiving only insulin therapy and high systolic blood pressure." (PMID 38874277, 2024). "This can assist persons with diabetes to achieve optimum blood glucose control, particularly for those using intensive insulin regimens to minimize hypoglycemia and manage hyperglycemia." (PMID 39507142, 2024). "The literature search was conducted with combinations of the following keywords: diabetes, β-cells, β-cell dysfunction, and insulin-producing cells." (PMID 38326874, 2024). "Diabetes mellitus (DM) is a metabolic disease characterized by disturbed insulin secretion or/and sensitivity leading to chronic hyperglycemia." (PMID 39691690, 2024). "Multivariate analysis was performed with or without adjustment for age, sex, smoking status, alcohol consumption, income status, BMI (kg/m2), hypertension, dyslipidemia, diabetes duration, insulin, and ≥3 oral hypoglycemic agents." (PMID 39435756, 2024). "Insulin analogues have been developed to improve the management of diabetes by mimicking the natural secretion of insulin, thereby reducing fluctuations in blood glucose levels." (PMID 38347465, 2024). "Defective insulin secretion by pancreatic beta cells is a key pathophysiological defect in type 2 diabetes mellitus (T2D)." (PMID 39338524, 2024). "These improvements aid in boosting glucose metabolism and insulin sensitivity, which are crucial for diabetes control." (PMID 38689329, 2024). "The clinical similarities between MODY2 and other diabetes types can complicate diagnosis, often resulting in misdiagnosis and inappropriate treatment with insulin or oral hypoglycemic agents." (PMID 39245718, 2024). "The use of non-invasive CGM data in dynamic modeling of the glucose-insulin system has the potential to advance precision nutrition as well as diabetes prevention and management." (PMID 38580749, 2024). "Insulin, the pioneering peptide therapeutic developed for diabetes treatment, approved for medical use in the early 1920s, has been playing a pivotal role in diabetes management." (PMID 38794282, 2024). "The most commonly used concomitant diabetes medications were insulin (130, 52.2%) and glycosidase inhibitors (104, 41.8%)." (PMID 38524632, 2024). "In humans, type 2 diabetes mellitus shows a higher prevalence in men compared with women, a phenotype that has been attributed to a lower peripheral insulin sensitivity in men." (PMID 38358819, 2024). "According to the outcomes of the existing study, metformin, a medication commonly prescribed for diabetes, has the potential to enhance cognitive function, alleviate stress, improve neurotransmitter activity, and enhance insulin pathways within the brain." (PMID 39585487, 2024). "The Diabetes Control and Complications Trial demonstrated the efficacy of intensive therapy involving multiple daily injections or continuous subcutaneous insulin infusion using short-acting (regular) and intermediate-acting (NPH) human insulins." (PMID 39065795, 2024). "Type 2 diabetes mellitus is a long-term metabolic disorder characterized by insulin resistance and inadequate insulin production, resulting in high levels of glucose in the blood." (PMID 39193371, 2024).
diabetes (continued). "Overall, SMA micelles offer a promising strategy for oral insulin delivery, potentially improving diabetes management." (PMID 39065795, 2024). "It has also been shown that the metabolic reserve of the heart is impaired in diabetes and this is due to the response of cardiomyocytes to insulin, stress and the changing amount of available FA." (PMID 38672121, 2024). "Diabetes mellitus (DM) is a type of chronic metabolic disease characterized by persistent hyperglycemia caused either due to the insufficiency or resistance factor function of insulin." (PMID 39575021, 2024). "Despite advancements in diabetes management, such as improved insulin delivery systems, many individuals fail to achieve optimal glycemic control, causing complications and a significant burden." (PMID 39411715, 2024). "Conversely, the inhibition of let-7, using let-7-specific antagomirs, enhances insulin sensitivity and provides remarkable resistance to high-fat-diet-induced obesity and diabetes." (PMID 39684593, 2024). "Oral medication is the most common medical treatment for DM, ranging between 6.7 − 14.4% of patients with diabetes, and subsequently insulin treatment, ranging between 4.2 − 9.7% of patients with diabetes." (PMID 39026315, 2024). "This article explores the potential of photoactivatable drugs in diabetes treatment, with a focus on light-activated insulin." (PMID 38542928, 2024). "Diabetes is an enduring metabolic condition identified by heightened blood sugar levels stemming from insufficient production of insulin or ineffective utilization of insulin within the body." (PMID 38665371, 2024). "Our findings on the regulation of blood glucose and plasma insulin levels in SITG-treated T2DM-induced rats underscore the possible neuroprotective effects of SITG against diabetes-induced neuronal degeneration." (PMID 39766390, 2024). "Since it has been reported that the treatment of isolated rat muscle with the AMPK activator AICAR increases GU via GLUT4 in an insulin-independent manner, the regulation of AMPK as well as insulin contributes to diabetes control." (PMID 38392186, 2024). "Animal model studies have also confirmed that bilirubin supplementation can improve glucose metabolism and insulin sensitivity, preventing the onset of diabetes." (PMID 39188917, 2024). "Treatment of β-cells the small molecule harmine promotes mitogenesis through a mild increase in c-Myc expression, suggesting the potential targeting of c-Myc in diabetes to improve insulin production." (PMID 39100099, 2024). "From the pointof view of improving diabetes, it has been shown that improved insulin secretionand insulin sensitivity as well as better glycemic control can be observed afterreducing the levels of body iron stores." (PMID 39484139, 2024). "Diabetes-prone rats with type 2 diabetes mellitus were administered insulin-loaded pectin hydrogels." (PMID 38279323, 2024). "Diabetes is a group of metabolic diseases characterised by hyperglycaemia resulting from defects in insulin secretion, insulin action, or both." (PMID 39655103, 2024). "Iterations in basal insulin have led to both a reduction innocturnal and daytime hypoglycemia,resulting in diabetes treatment guidelines recommending IDeg and IGlar U300 as preferredbasal insulin therapies." (PMID 38224978, 2024). "Our findings showed that 80.8% of patients with diabetes were treated with glucose-lowering agents (oral or insulin) at discharge and 86.3% at one-year follow-up." (PMID 39227843, 2024). "Type 2 diabetes mellitus (T2D) is a metabolic condition depicted by chronic hyperglycemia, inadequate insulin secretion or activity, and impaired insulin sensitivity, also known as insulin resistance (IR)." (PMID 39627194, 2024). "These two indicators can measure β-cell function adjusted for insulin sensitivity and predict the development of diabetes over ten years." (PMID 39886031, 2024).